BAG1 (BAG cochaperone 1)
Diseases named in the same sentence as BAG1 in open-access papers (continued):
Sharing a sentence is not in itself a finding about the gene and the disease.
breast carcinoma (continued). "Our investigation reveals a protective role for BAG-1 in HER2+ breast cancer and provides insight into the mechanism by which increased BAG-1 protein expression supports cell viability by attenuating the growth-inhibitory effect of trastuzumab." (PMID 26958811, 2016). "In breast xenograft studies, BAG-1 overexpression drives growth of oestrogen-responsive ZR-75–1 breast cancer cells in an oestrogen-dependent manner." (PMID 26958811, 2016). "The H2-Penetratin peptide has been demonstrated to bind the ATPase domain of HSC70 and exert its effects, such as growth inhibition, in human breast cancer cells by preventing the interaction between BAG-1 and HSC7020." (PMID 27633857, 2016). "The co-chaperone protein Bcl-2-associated athanogene 1 (BAG-1) exists as three main isoforms BAG-1S, BAG-1M, and BAG-1L and is frequently overexpressed in breast cancer and preinvasive breast disease." (PMID 26958811, 2016). "Our data indicate that BAG-1 overexpression can support growth of HER2+ breast cancer cells and reduces the growth-inhibitory effect of trastuzumab both in short and long-term cultures." (PMID 26958811, 2016). "Bag-1 has been reported to be upregulated in a number of malignancies including gastric cancer, cervical carcinoma, breast cancer, and colorectal cancer." (PMID 25962180, 2015). "Numerous studies have shown that Bag-1 is a multifunctional anti-apoptotic protein and that it is involved in several cancer types including gastric cancer, cervical carcinoma, breast cancer, and colorectal cancer." (PMID 25962180, 2015). "BAG-1 is also over-expressed in several human malignancies, especially in human breast cancer and cervical cancer." (PMID 22567091, 2012). "For example, BAG-1 is frequently overexpressed in breast cancer and can correlate with important clinical parameters." (PMID 19293798, 2009). "As ER-mediated regulation of cell growth, proliferation and survival are key components of breast cancer development, the role of BAG-1 as a predictive and prognostic marker in breast cancer requires further investigation." (PMID 19066611, 2009). "In breast cancer cell lines, Bag-1 prevents cells from undergoing apoptosis and protects cells from other forms of stress, including radiation, chemotherapy and hypoxia." (PMID 18430249, 2008). "ZR-75-1 breast cancer cells stably transfected with Bag-1 have increased survival in culture, and form larger tumors than nontransfected cells when injected into mammary fat pads of mice." (PMID 18430249, 2008). "Most of the literature, however, supports an anti-apoptotic role of Bcl-2 and Bag-1 in early-stage breast cancer, which appears to be related to the transcriptional function of ER." (PMID 18430249, 2008). "To address these issues, we assessed expression of Bag-1 on a large cohort of primary breast cancers using tissue microarrays, employing a new method of automated, quantitative analysis." (PMID 18430249, 2008). "A number of relatively small cohort studies have assessed expression of Bag-1 in breast cancer, with divergent results." (PMID 18430249, 2008). "Despite the interesting and encouraging results obtained from studies of BAG-1 in breast cancer, the ability of BAG-1 overexpression to promote tumour formation in transgenic animals is yet to be tested." (PMID 12373595, 2002). "A consistent finding is that relatively high levels of cytoplasmic BAG-1 expression are detected in two thirds or more cases of breast cancer." (PMID 12373595, 2002).
breast carcinoma (continued). "Some of the results from these studies are inconsistent and further studies are required to fully understand the role of BAG-1 expression in breast cancer." (PMID 12373595, 2002). "A correlation between ER and BAG-1 was also evident in breast cancer derived cell lines, as all lines examined with functional ER expression also expressed high levels of BAG-1." (PMID 10576663, 1999). "In addition, immunostaining of breast cancer cells provided insights into the cellular distribution of Bag‐1, and its interaction partners HSP70 and HSP27, as well as the phosphorylation mediator HER2." (PMID 39049197, 2024). "The association between Bag‐1 and the proteasome, as well as its interaction with HSP70, may be crucial for the survival of breast cancer cells." (PMID 39049197, 2024). "Thus, the results of the present study demonstrated that PI3K signaling pathways were activated in breast cancer cells overexpressing Bag‐1." (PMID 39049197, 2024). "The top autosomal DNAm sites were mapped to genes that have been associated with breast cancer and other malignancies (e.g., cg02325951 on FOXN3, cg20262915 and cg19765154 on NAB1, and cg07850329 on BAG1), as well as childhood neurodegeneration (e.g., cg12607525 on UBTF)." (PMID 36966332, 2023). "Moreover, according to the isoform-specific interactome analysis, protein processing, and ER-associated protein degradation (ERAD) pathways were controlled by Bag-1 expression in protein homeostasis of breast cancer." (PMID 37533517, 2022). "To assess whether observed differences among MCF-7 and MCF-12A cells reflect cancer-related alterations, we examined protein-protein interactions involving Bag-1 in normal and tumor tissues from breast cancer patients." (PMID 34428256, 2021). "Several studies on breast cancer suggested that BAG1 is a prognostic marker in breast cancer." (PMID 33925460, 2021). "Further studies may reveal Bag-1/Beclin 1 complex as a targetable component of autophagic progress in breast carcinomas." (PMID 33561998, 2021). "Therefore, the effects of Bag-1 overexpression in cultured breast cells were in line with the observations in breast cancer patients in terms of C-Raf, B-Raf and Akt expression and activation dynamics." (PMID 31883527, 2019). "Bag-1 is an anti-apoptotic protein and is overexpressed in breast cancer." (PMID 31883527, 2019). "Despite these differences, Bag-1 overexpression was a common feature in all breast cancer subtypes." (PMID 31883527, 2019). "Hence, Bag-1-induced effects in breast cell lines were similar to the observed alterations in breast cancer tumors." (PMID 31883527, 2019). "As previous review, evidence supporting the hypothesis that BAG-1 plays an important role in breast cancer has increased." (PMID 28510570, 2017). "Moreover, high nuclear BAG-1 immunoreactivity is an independent predictor of outcome particularly in patients with ER+ early breast cancer receiving adjuvant hormonal therapy, and enhances the predictive power of IH4 staining." (PMID 28510570, 2017). "To address the significance of BAG-1 as a biomarker in breast cancer, we have performed a systematic review against the REporting Recommendations for Tumour MARKer and Prognostic Studies (REMARK) criteria, which provide a framework for reporting of studies of cancer biomarkers." (PMID 28510570, 2017). "BAG-1 could be a candidate predictive biomarker by enabling the definition of breast cancer patient subgroups likely to display de novo resistance to trastuzumab." (PMID 26958811, 2016). "Proof-of-principle studies from our laboratory show that it is possible to restrict breast cancer cell growth by targeting BAG-1 protein-protein interactions using synthetic peptides and small molecule compounds, like Thioflavin S (Thio-S) and its biologically potent constituent Thio-2." (PMID 26958811, 2016). "Targeting BAG-1 might therefore constitute a potential therapeutic option for HER2+ breast cancers refractory to trastuzumab." (PMID 26958811, 2016).
breast carcinoma (continued). "Furthermore, high BAG-1 expression remained an independent prognostic predictor (p = 0.022) of death from breast cancer in a multivariate model comprising standard clinicopathological variables." (PMID 26958811, 2016). "The observed increase in BAG-1 expression in HER2+ breast cancer cells raised the possibility that certain HER2+ cells may be dependent on BAG-1 for growth in response to the HER2-targeted therapy trastuzumab." (PMID 26958811, 2016). "In addition, BAG-1 expression is often altered in various human malignancies, especially in human breast cancer, lung cancer and cervical cancer." (PMID 22567091, 2012). "For example, BAG-1 isoforms are potential molecular markers for the pathogenesis of breast cancer." (PMID 22179630, 2012). "In breast cancer, overexpression of Bag-1 has been detected in a majority of cases." (PMID 20969773, 2010). "Furthermore, for breast cancer-specific death, BAG-1 expression was of superior predictive power to tumour grade, tumour size and lymph node status." (PMID 19066611, 2009). "Consequently, we aimed to define the relationship of BAG-1 expression with outcome and response to therapy in a large cohort of early breast cancer patients of uniform histological type with well-documented treatment and follow-up data." (PMID 19066611, 2009). "To provide some potential mechanistic insights into the relationship between high BAG-1 expression and improved outcome in ER+ tamoxifen-treated patients, we assessed the effect of BAG-1 overexpression on oestrogen/antioestrogen sensitivity in ER+ MCF-7 breast cancer cells." (PMID 19066611, 2009). "The overexpression of BAG-1 has been described in several breast cancer cell lines, with the three isoforms demonstrating differing intracellular localisations: BAG-1L is predominantly nuclear, BAG-1S is predominantly cytoplasmic and BAG-1M is present in both the cellular compartments." (PMID 19066611, 2009). "A high BAG-1 expression predicts improved patient outcome in ER+ breast carcinoma." (PMID 19066611, 2009). "In the present work we assessed expression of Bcl-2 and Bag-1 in primary breast cancer specimens." (PMID 18430249, 2008). "Several preclinical studies have demonstrated the importance of Bag-1 in breast cancer." (PMID 18430249, 2008). "Evaluation of Bcl-2 and Bag-1 expression in breast cancer may identify a subset of patients with a favorable prognosis, who might not benefit from chemotherapy or who might benefit from Bcl-2 targeting agents in addition to antihormonal therapy." (PMID 18430249, 2008). "Evidence that BAG-1 expression is frequently altered in human cancers, in particular in breast cancer, relative to normal cells has been put forward but the notion that overexpression of BAG-1 contributes to poor prognosis in tumorigenesis remains controversial." (PMID 15560850, 2004). "Further work, including prospective trials, are required to confirm the exciting possibility that BAG-1 expression might be used as a prognostic marker in early breast cancer." (PMID 12373595, 2002). "However, other studies of BAG-1 expression in breast cancer and other cancer types have yielded differing results." (PMID 12373595, 2002). "In addition, discrepant results regarding BAG-1 immunostaining and patient survival in early breast cancer have been in dispute." (PMID 12402153, 2002). "Studies have focused on breast cancer, non-small cell lung cancer and squamous cell carcinoma of the head and neck, and there are indications that BAG-1 expression may also be altered in glioblastoma, cervical cancer and haemopoietic malignancies." (PMID 12373595, 2002). "A change in antigen retrieval technique or scoring threshold might alter the proportion of tumours that are considered to be positive for expression and might contribute to the variation in detection of nuclear BAG-1 expression in breast cancer." (PMID 12373595, 2002).
breast carcinoma (continued). "In addition to the prototypical 36 kDa BAG-1 isoform, breast cancer cells expressed higher molecular weight isoforms and, in contrast to BCL-2, BAG-1 expression was independent of oestrogens." (PMID 10576663, 1999). "Collectively, the results of the present study highlighted that Bag‐1 overexpression in HER2+ breast cancer cells, specifically BT‐474 cells, may regulate the expression of HSPs through promoting HSF1 phosphorylation at Ser326, through the PI3K/AKT/mTOR pathway." (PMID 39049197, 2024). "Besides, BAG1 was reported to be a protective factor in breast cancer." (PMID 34721517, 2021). "We first tested whether Bag-1 was overexpressed in all molecular subtypes of breast cancer." (PMID 31883527, 2019). "Moreover, after hormone binding, BAG-1 is able to influence receptor-mediated transcription of the nuclear hormone-responsive genes e.g. BAG-1 has been shown to interact with and stimulate the activity of both ERα and ERβ, and enhance E2-dependent transcription in breast cancer cells." (PMID 27633857, 2016). "Also, overexpression of the Bag1 gene in mammary carcinomas may limit the efficacy of PPARγ agonists, like 15-deoxy-PGJ2, as apoptosis-inducing agents." (PMID 19399228, 2009). "However, the critical functional requirement for the BAG domain seemed to be chaperone binding as the introduction of mutations that specifically ablated HSC70/HSP70 interaction interfered with BAG-1-mediated survival in breast cancer cells and other cell systems." (PMID 19293798, 2009). "BAG-1 potentiates activity of oestrogen receptors (ER) (R Cutress, PA Townsend and G Packham, unpublished data), which mediates proliferative, and survival responses to oestrogens in hormone dependent breast cancers and is the target for anti-hormone therapies such as tamoxifen." (PMID 12373595, 2002). "Changes in BAG-1 expression can be detected in benign lesions such as sclerosing adenosis, and in ductal carcinoma in situ suggesting that they might represent a relatively early event in breast cancer development." (PMID 12373595, 2002). "Therefore, analysis of expression of BAG-1 in human breast cancer is of considerable interest." (PMID 10576663, 1999). "These metabolites can act through intervening in breast cancer targets such as SARM1, RGS5, BAG1, PROM2, and NEAT1." (PMID 40223933, 2025). "BAG1 explicitly enhances the expression of HSP70 and HSP27, contributing to breast cancer cell survival and, potentially, drug resistance." (PMID 39850800, 2024). "Blocking the interaction between HSC70 and BAG-1 via BAG-1-derived peptides inhibited cell proliferation in MCF-7 and ZR-75-1 breast cancer cells." (PMID 38255948, 2024). "The findings in this study highlighted the functional role of Bag-1 on the PI3K/Akt signaling axis, which orchestrates cell cytoskeleton targets in MCF-7 breast cancer cells." (PMID 34995286, 2022). "The clinical relevance of Bag-1 was shown as a prognostic biomarker in Oncotype DX and PAM50 assay, which highlighted its role in breast cancer." (PMID 37533517, 2022). "The focal CNAs contained several cancer relevant genes, such as the known breast cancer genes EGF, CDKN2A and BAG1 and some were less established including ZAR1 and BMS1." (PMID 33168853, 2020). "To better understand the mechanism of Bag-1-mediated cell survival in breast cancer cell lines, we investigated phosphorylation levels of Bad protein in MCF-7, BT-474 and MDA-MB-231 cells after transfection with Bag-1 plasmid or Bag-1 siRNA." (PMID 31883527, 2019). "One study failed to give any precise subcellular analysis, but stated that staining for BAG-1 was mixed, with more cytosolic than nuclear BAG-1 in breast carcinomas." (PMID 28510570, 2017). "In this study we show for the first time that elevated BAG-1 protein expression correlates with that of HER2, is important for optimal growth of some HER2-overexpressing breast cancer cells, and impedes the growth-inhibitory effect of trastuzumab." (PMID 26958811, 2016).
breast carcinoma (continued). "Thus, the present study aimed to determine the interactions between Bag‐1 and HSPs (HSP90, HSP70 and HSP27) that contribute to HSF1 phosphorylation in breast cancer cells." (PMID 39049197, 2024). "In another study, the overexpression of Bag-1, another protein from the BAG family, modulates HSP levels by phosphorylating HSF1 at Ser326 via the PI3K/AKT/mTOR pathway in HER2-positive and HER2-negative breast cancer cells." (PMID 39850800, 2024). "The present study aimed to determine the interactions between Bag‐1 and heat shock proteins (HSPs); namely, HSP90, HSP70 and HSP27, to elucidate their role in promoting heat shock factor‐1 (HSF1)‐dependent survival of breast cancer cells." (PMID 39049197, 2024). "According to previous studies, while the transient silencing of Bag-1 enhanced drug-induced apoptosis, deletion of BAG-1 could induce stemness properties and Akt-mediated actin remodeling in MCF-7 breast cancer cells." (PMID 37533517, 2022). "Several studies explained the anti-apoptotic potential and survival-targeted role of Bag-1 expression in cancer, whereas the effect of complete knockout of Bag-1 in breast cancer has not been revealed in depth yet." (PMID 34995286, 2022). "In the clinical setting, BAG-1 mRNA has been incorporated as a prognostic biomarker in Oncotype DX and PAM50 multigene assays, which estimate prognosis following surgery, and can be used to assess the potential benefit of chemotherapy for breast cancer." (PMID 28510570, 2017). "The BAG-1L isoform specifically binds to and increases the transcriptional activity of oestrogen receptor in cells, and in some, but not all studies, BAG-1 expression is predictive of clinical outcome in breast cancer." (PMID 28510570, 2017). "Nevertheless, these observations are not mutually exclusive; since BAG-1 enhances ER transcription and can stimulate ER activity, it would be expected to support growth of breast cancers that are reliant on BAG-1 related pathways." (PMID 26958811, 2016). "We next examined BAG-1 protein immunoreactivity in a panel of breast cancer cell lines representing distinct disease subtypes and in non-tumorigenic MCF10A mammary epithelial cells." (PMID 26958811, 2016). "OncomineTM (Compendia Bioscience, Ann Arbor, MI) was used to analyze BAG-1 gene expression in the Molecular Taxonomy of Breast Cancer International Consortium (METABRIC) dataset, comprising 1971 patients of which there were 506 deaths due to breast cancer." (PMID 26958811, 2016). "We determined relationships between BAG-1 expression, molecular phenotype, response to tamoxifen therapy and outcome in a cohort of breast cancer patients and its influence on tamoxifen sensitivity in MCF-7 breast cancer cells in vitro." (PMID 19066611, 2009). "The survival-promoting function of BAG-1 was dependent on the BAG domain as a BAG-1 mutant lacking this region failed to promote cell survival in breast cancer cells." (PMID 19293798, 2009). "The mechanism of overexpression of BAG-1 in breast cancer is also not known although in prostate cancer it is amplified in 7.4% of hormone-refractory cancers." (PMID 19066611, 2009). "Another possible explanation for our findings is that in good-prognosis breast cancer tumors, Bcl-2 and Bag-1 have other dominant roles that are not related to their anti-apoptotic functions." (PMID 18430249, 2008). "Ninety genes belonging to the GO category of 'apoptosis', including members of the BAG family (BAG1, BAG2, BAG3), as well as members of the breast cancer 'proliferation signatures' (BUB1, PLK1, CCNE1, CCND1 and CCNB1) were also identified as up-regulated in our DTET." (PMID 17014703, 2006). "Further work is required to assess the ability of BAG-1 to predict response to adjuvant therapy, in particular given the role of BAG-1 in modulation of NHR function, and the importance of adjuvant hormonal therapy in breast cancer." (PMID 12373595, 2002).